UNC5B (unc-5 netrin receptor B)
Description:
Receptor for netrin required for axon guidance. Mediates axon repulsion of neuronal growth cones in the developing nervous system upon ligand binding. Axon repulsion in growth cones may be caused by its association with DCC that may trigger signaling for repulsion (By similarity). Functions as a netrin receptor that negatively regulates vascular branching during angiogenesis. Mediates retraction of tip cell filopodia on endothelial growth cones in response to netrin (By similarity). It also acts as a dependence receptor required for apoptosis induction when not associated with netrin ligand. Mediates apoptosis by activating DAPK1. In the absence of NTN1, activates DAPK1 by reducing its autoinhibitory phosphorylation at Ser-308 thereby increasing its catalytic activity (By similarity).
Synonyms: p53RDL1; UNC5H2
Tractability: Antibody: UniProt places it where antibodies can reach, with high confidence; its Gene Ontology location is reachable by antibodies, with high confidence; UniProt predicts a signal peptide or a membrane-spanning region. PROTAC: ubiquitination databases record sites on it.
Gene: Protein-coding gene on chromosome 10 (71,212,523 to 71,302,885, forward strand). Ensembl gene ENSG00000107731.
Subcellular location: Cell membrane; Membrane raft
Pathways (Reactome):
Developmental Biology: Netrin mediated repulsion signals; Netrin-1 signaling
Programmed Cell Death: Caspase activation via Dependence Receptors in the absence of ligand
Gene Ontology:
Molecular function: protein binding; netrin receptor activity
Biological process: negative regulation of extrinsic apoptotic signaling pathway in absence of ligand; negative regulation of neuron apoptotic process; positive regulation of phosphatidylinositol 3-kinase/protein kinase B signal transduction; anterior/posterior axon guidance; netrin-activated signaling pathway; signal transduction
Cellular component: plasma membrane; membrane raft; membrane
Genetic constraint (gnomAD): Loss-of-function variants: 56 observed, 101.04 expected, observed/expected ratio (o/e) 0.55, 90% interval 0.45 to 0.69. The upper end of that interval is the gene's LOEUF score, 0.69, which puts it in group 2 of 6, group 1 being the genes least tolerant of losing a copy. Missense variants: 1,194 observed, 1,284.5 expected, observed/expected ratio (o/e) 0.93, 90% interval 0.89 to 0.98. Synonymous variants: 577 observed, 539.28 expected, observed/expected ratio (o/e) 1.07, 90% interval 1 to 1.15.
Homologues: Orthologues: chimpanzee UNC5B (99% identical), macaque UNC5B (99% identical), dog UNC5B (96% identical), pig UNC5B (94% identical), guinea pig UNC5B (93% identical), mouse Unc5b (92% identical), rabbit UNC5B (92% identical), rat Unc5b (91% identical), tropical clawed frog unc5b (79% identical), zebrafish unc5b (67% identical), Drosophila melanogaster unc-5 (32% identical), Caenorhabditis elegans unc-5 (30% identical). Paralogues in human: UNC5C (63% identical), UNC5D (52% identical), UNC5A (46% identical), UNC5CL (14% identical).
Diseases named in the same sentence as UNC5B in open-access papers:
UNC5B is named in the same sentence as 83 diseases in open-access papers, as found by Europe PMC text mining. Sharing a sentence is not in itself a finding about the gene and the disease. The quoted sentences say what the papers report.
bladder cancer (13 papers, 2014 to 2024). "Higher levels of UNC5B expression were associated with a poor prognosis and a short overall survival time in people with bladder cancer." (PMID 38546656, 2024). "Conversely, low PKC activity, low NTN1 expression and high UNC5B expression can increase the susceptibility of bladder cancer cells to chemical therapeutics." (PMID 38546656, 2024). "The present study aims to investigating the clinical significance of PKC α, netrin-1 and UNC5B in bladder cancer as well as their association with malignant biological behavior of cancer cells." (PMID 24528886, 2014). "Furthermore, netrin-1/UNC5B was closely associated with bladder cancer malignant pathological biological behavior." (PMID 24528886, 2014). "UNC5B overexpression in 5637 BC cells decreased cell multiplication and migration, as well as produced cell cycle arrest in the G2/M phase, with alterations in the expression of cell cycle‐associated proteins, indicating that UNC5B may suppress bladder cancer cells' metastatic tendencies." (PMID 38546656, 2024). "UNC5B overexpression in 5637 cells inhibited cell multiplication and migration and induced cell cycle arrest at the G2/M phase, meanwhile exhibited changes in the expression of cell cycle-associated proteins, showing that UNC5B may inhibit metastatic behaviors in bladder cancer cells." (PMID 27846823, 2016). "EDU assay, apoptosis, xenograft tumour implantation, migration, invasion and tumour metastasis were performed to comprehensively identify the effects of UNC5B truncates on bladder cancer cells." (PMID 33345442, 2021). "Previous studies revealed that UNC5B overexpression inhibits proliferation in human bladder cancer cells." (PMID 34239689, 2021). "In particular, although PKCα does not regulate the cell cycle of bladder cancer through the NF‐kB signalling pathway, previous studies have found that PKCα can regulate the expression of UNC5B, and UNC5B can regulate the cell cycle of bladder cancer." (PMID 33452764, 2021). "In the current study, we have found for the first time that miR-424, a direct target of HIF-1α, decreases CDDP sensitivity of bladder cancer cells through down-regulation of pro-apoptotic UNC5B and SIRT4." (PMID 32522234, 2020). "In the present study, we have described for the first time that HIF-1α-mediated induction of miR-424 causes down-regulation of pro-apoptotic UNC5B and SIRT4, thereby inhibiting CDDP-dependent apoptotic cell death of bladder cancer cells." (PMID 32522234, 2020). "CDDP-mediated suppression of xenograft bladder tumor growth was prohibited by the addition of miR-424, whereas ectopic expression of UNC5B or SIRT4 partially restored miR-424-dependent decrease in CDDP sensitivity of bladder cancer 5637 and T24 cells." (PMID 32522234, 2020). "Evidences showed that UNC5B, a target gene of miR-129-5p, act as a tumor suppressor in various cancers such as bladder cancer and pancreatic cancer." (PMID 32760219, 2020). "Inverse correlations between miR-424 and UNC5B or SIRT4 expression levels in bladder cancer tissues further supported the negative regulation of UNC5B and SIRT4 by miR-424 in vivo." (PMID 32522234, 2020). "Collectively, these results indicate that miR-424 suppresses CDDP-mediated bladder cancer cell death through down-regulation of UNC5B and SIRT4 in vivo." (PMID 32522234, 2020). "Based on our present results, forced expression of miR-424 mimics reduced UNC5B and SIRT4 expressions in bladder cancer 5637 and T24 cells, whereas miR-424 inhibitor increased UNC5B and SIRT4 expressions in these cells." (PMID 32522234, 2020). "There existed a clear inverse relationship between the expression levels of miR-424 and pro-apoptotic UNC5B or SIRT4 in bladder cancer tissues." (PMID 32522234, 2020).
bladder cancer (continued). "Most recently, UNC5B was reported to inhibit proliferation and migration by inhibiting cell cycle progression at the G2-M phase in bladder cancer cells." (PMID 29221192, 2017). "Our group has reported the novel function of PKCα in bladder cancer where it regulates cell survival through the netrin-1/UNC5B pathway, and by targeting DICER, PKCα can also modulate apoptosis of UCC cell lines." (PMID 28629334, 2017). "Stable transfection of the human bladder cancer cell line 5637 with UNC5B (5637-U) was confirmed by real-time RT-PCR, western blot and immunofluorescence assays." (PMID 27846823, 2016). "We observed that tumors derived from 5637-U cells grew at a slower rate and were smaller than tumors derived from 5637 cells (P = 0.004), implicating UNC5B as a candidate tumor suppressor in bladder cancer." (PMID 27846823, 2016). "In-depth studies of UNC5B in tumors have revealed that UNC5B is down-regulated in bladder cancer tissues and that lower UNC5B expression is an independent determinants for recurrence of bladder cancer." (PMID 27846823, 2016). "Our results suggest that UNC5B overexpression inhibits the proliferation and migration of bladder cancer cells by inducing cell cycle arrest at G2/M phase." (PMID 27846823, 2016). "Our findings suggest that UNC5B is a potential anti-neoplastic target in bladder cancer progression." (PMID 27846823, 2016). "In this study, we detect the expression of netrin-1/UNC5B in the bladder cancer tissues as well as in the bladder cancer cell line on both the RNA and protein levels, we found that netrin-1/UNC5B was closely related to the activation of PKC alpha state." (PMID 24528886, 2014). "Netrin-1 and UNC5B expression was examined in 120 bladder cancer specimens using immunohistochemistry and in 40 fresh cancer tissues by western blot." (PMID 24528886, 2014). "Immunofluorescence showed elevated netrin-1 and decreased UNC5B expression in bladder cancer cells compared with normal bladder cell line." (PMID 24528886, 2014). "UNC5B showed lower expression in bladder cancer tissues compared with adjacent normal tissues." (PMID 38546656, 2024). "Consequently, PKCα and NTN1/UNC5B work together to regulate the effects of cisplatin on bladder cancer cells through a positive feedback regulatory loop." (PMID 38546656, 2024). "Furthermore, strong PKC activity, high NTN1 expression and low UNC5B expression can improve bladder cancer cells cisplatin tolerance." (PMID 38546656, 2024). "In addition, we reveal that overexpressing the intracellular domain of UNC5B cannot bind or activate cleaved caspase‐3 to trigger apoptosis in bladder cancer cells." (PMID 33345442, 2021). "PKC alpha regulated the trin-1/UNC5B-mediated survival pathway in bladder cancer." (PMID 32802870, 2020). "Next, we asked whether there could exist the correlation between miR-424 and UNC5B or SIRT4 expression levels in our bladder cancer samples (n = 30)." (PMID 32522234, 2020). "In summary, UNC5B is a potential tumor suppressor in bladder cancer; however, the precise mechanism by which UNC5B influences bladder cancer progression remains unclear and merits further investigation." (PMID 27846823, 2016). "In this study, we investigated the role of UNC5B in bladder cancer in vitro and in vivo." (PMID 27846823, 2016). "Therefore, we need to validate that PKC α inhibits bladder cancer cell apoptosis by regulating signaling pathway of netrin-1/UNC5B." (PMID 24528886, 2014). "Therefore, we suggested that PKCα may regulate the cell cycle of bladder cancer by regulating UNC5B." (PMID 33452764, 2021). "Additionally, siRNA-mediated silencing of either UNC5B or SIRT4 resulted in a significant decrease in the sensitivity to CDDP of bladder cancer 5637 and T24 cells, whereas miR-424-mediated decrease in CDDP sensitivity was partially restored by forced expression of UNC5B or SIRT4." (PMID 32522234, 2020).
bladder cancer (continued). "Therefore, we hypothesized that UNC5B signaling plays a key role in the development of bladder cancer." (PMID 27846823, 2016). "Taken together, these data show that UNC5B may suppress the progression of bladder cancer." (PMID 27846823, 2016). "Unc5b is one of the common receptors of netrin-1 and netrin-1 -Unc5b pathway has been involved in PDAC tumors, bladder cancer and renal cell carcinoma." (PMID 35974411, 2022). "In this study, different UNC5B truncates (residue 399‐945, residue 412‐945) were created to explore whether the caspase‐3 cleavage site (site 412), as another potential functional domain of its intracellular portion, could be activated to induce apoptosis in bladder cancer cells." (PMID 33345442, 2021). "However, the functional significance of UNC5B overexpression in bladder cancer remains unclear." (PMID 27846823, 2016). "The present study identified netrin-1/UNC5B, which could be regulated by PKC signaling, was important mediators of bladder cancer progression." (PMID 24528886, 2014). "However, in our previous studies, we found that the death domain of UNC5B in bladder cancer cells could not be activated to promote apoptosis." (PMID 33345442, 2021). "Therefore, it is suggestive that HIF-1α/miR-424/UNC5B/SIRT4 regulatory axis contributes to the acquisition and/or the maintenance of CDDP resistance of bladder cancer cells irrespective of hypoxia." (PMID 32522234, 2020).
breast carcinoma (8 papers, 2016 to 2025). "Our findings highlight the significance of UNC5B in breast cancer, including its promising diagnostic and prognostic value and potential as a therapeutic target." (PMID 32902412, 2020). "In summary, UNC5B is a promising diagnostic and prognostic biomarker and targeting UNC5B is a potential strategy for individualized breast cancer treatment." (PMID 32902412, 2020). "Considering the close association of UNC5B with breast cancer, UNC5B could act as a potential diagnostic marker of breast cancer." (PMID 32902412, 2020). "Our data revealed that upregulated UNC5B expression in breast cancer could be a promising diagnostic biomarker." (PMID 32902412, 2020). "Moreover, the molecular function and underlying mechanism of UNC5B in breast cancer are unclear." (PMID 32902412, 2020). "Among these genes, UNC5B has been reported to be significantly upregulated in breast cancer and is correlated with poor overall survival in breast cancer patients." (PMID 40631077, 2025). "The results of the IHC staining revealed that high UNC5B protein expression was correlated with poor OS in breast cancer patients (p = 0.0125)." (PMID 32902412, 2020). "Here, we showed that UNC5B expression was significantly upregulated in breast cancer using bioinformatics analysis and experimental validation." (PMID 32902412, 2020). "Consistently, the silencing of UNC5B compromised the colony formation ability of breast cancer cells." (PMID 32902412, 2020). "UNC5B knockdown inhibited breast cancer cell proliferation and metastasis and compromised PI3K/Akt signaling activation." (PMID 32902412, 2020). "To elucidate the specific role of UNC5B in breast cancer, we performed shRNA-mediated UNC5B knockdown in T-47D and MDA-MB-231 breast cancer cells." (PMID 32902412, 2020). "UNC5B was altered in 24 of 180 (13%) breast cancer patients, and amplification was the most frequent type of UNC5B alteration in breast cancer (10.13%)." (PMID 32902412, 2020). "UNC5B mRNA expression was consistently higher in breast cancer tumors than in adjacent normal tissues (p < 0.001)." (PMID 32902412, 2020). "Collectively, these results emphasized the essential role of UNC5B in breast cancer cell proliferation and metastasis." (PMID 32902412, 2020). "We also noted that UNC5B inhibition attenuated the proliferation and metastasis of breast cancer cells and demonstrated that UNC5B depletion inhibited PI3K/Akt signaling." (PMID 32902412, 2020). "Significant changes in UNC5B expression at the transcriptional level between different histological subtypes of breast cancer and normal breast tissues (ONCOMINE)." (PMID 32902412, 2020). "To understand how UNC5B influences breast cancer prognosis, we analyzed the expression of UNC5B and its prognostic value in breast cancer using the TCGA data in GEPIA." (PMID 32902412, 2020). "The silencing of UNC5B significantly suppressed the migration and invasion capacities of breast cancer cells." (PMID 32902412, 2020). "Across gender, race, menopause status, molecular subtypes, and cancer stages, UNC5B mRNA expression was always higher in breast cancer patients than in healthy individuals." (PMID 32902412, 2020). "In the present study, we demonstrated for the first time that UNC5B mRNA expression was significantly higher in breast cancer tissues than in normal breast tissues using transcriptional data from more than 1,000 breast cancer samples in diverse databases." (PMID 32902412, 2020). "As expected, UNC5B expression was upregulated in eight breast cancer cell lines compared to MCF 10A cells." (PMID 32902412, 2020). "As expected, UNC5B depletion significantly attenuated the proliferation of breast cancer cells (p < 0.01)." (PMID 32902412, 2020). "Note that white breast cancer patients tended to have higher UNC5B expression than African-American patients (p < 0.001) and Asian patients (p < 0.05), implying ethnic diversity of UNC5B expression." (PMID 32902412, 2020).